LGALS3 (galectin 3)
Diseases named in the same sentence as LGALS3 in open-access papers (continued):
Sharing a sentence is not in itself a finding about the gene and the disease.
Ureteral obstruction (8 papers, 2014 to 2025). Obstruction of the flow of urine through the ureter. "In glomeruli of STZ + HFD mice, >80 % of MRP8 signals co-localize with macrophage marker Mac2 (or Lgals3), whereas collecting duct epithelial cells are the main source of MRP8 expression in unilateral ureteral obstruction." (PMID 24357461, 2014).
Ventricular arrhythmia (8 papers, 2020 to 2024). "The authors found that the plasma concentration of galectin-3 in patients diagnosed with ventricular arrhythmia was significantly higher compared to its level in healthy children." (PMID 35410028, 2022). "However, those are the initial reports in a small cohort and are not conclusive enough to introduce galectin-3 into the standard panel of measurements in patients with ventricular arrhythmia in daily practice." (PMID 35410028, 2022).
B cell lymphoma (7 papers, 2016 to 2025). "In line with this, the induction of B cell lymphoma cell death by Galectin-1 and Galectin-3 also depended on the surface glycosylation of these cells." (PMID 40641998, 2025).
brain tumors (7 papers, 2010 to 2025). "In children, galectin-3 has previously been investigated as an inflammatory marker in chronic hepatitis B infection, juvenile idiopathic arthritis, or brain neoplasms." (PMID 29327139, 2018). "Based on this data the authors conclude that galectin-3 is differentially expressed in various brain tumors, and thereby, is a helpful biomarker in making differential diagnoses, especially in cases where a morphological diagnosis is controversial." (PMID 23658855, 2010). "In the latest study researchers investigated galectin-3 expression in 409 cases of surgically resected primary brain tumors, including various glio-neuronal tumors, pituitary adenomas, meningiomas and Schwannomas." (PMID 23658855, 2010). "Another study suggested that the expression level of LGALS3 might affect macrophage infiltration in brain tumors, but only 16 GBM samples were used in their study." (PMID 32528967, 2020). "For example, disrupting the interaction between CHI3L1 and Galectin-3 (Gal3) using GMP, a Gal3-binding peptide mimetic, inhibits M2-TAM polarization and supports T cell proliferation in brain tumors." (PMID 41019045, 2025).
chronic lymphocytic leukemia (7 papers, 2015 to 2025). "The Chronic Lymphocytic Leukemia (Broad, Nature 2015) RNAseq dataset was analysed using the cBioPortal in regard to the expression of class II HLA genes and the conventional LAG-3 ligands: FGL1, LGALS3." (PMID 40136700, 2025). "Galectin-3’s (Gal-3) effect on the pathogenesis of chronic lymphocytic leukemia (CLL) has not yet been extensively studied." (PMID 38201234, 2023).
Crohn disease (7 papers, 2009 to 2025). A gastrointestinal disorder characterized by chronic inflammation involving all layers of the intestinal wall, noncaseating granulomas affecting the intestinal wall and regional lymph nodes, and transmural fibrosis. "While none of the biomarkers presented a statistically significant correlation with disease activity scores in IBD patients, a notable association (r = 0.603, p < 0.05) was observed between galectin-3 and CRP levels in patients with Crohn’s disease." (PMID 41226478, 2025). "The only significant, positive correlation was observed between galectin-3 and CRP (r = 0.603, p < 0.05) concentrations in patients with Crohn’s disease, suggesting a potential link between galectin-3 and systemic inflammatory response in this subgroup." (PMID 41226478, 2025). "Suggesting a connection to the antibody-mediated response, serum from Crohn's disease patients was shown to contain anti-galectin-3 IgG antibodies." (PMID 19500416, 2009). "A reduced expression of galectin-3 has been found in intestinal macrophages of patients with Crohn's disease but not in UC patients." (PMID 26885508, 2016).
diabetic cardiomyopathy (7 papers, 2011 to 2025). Diabetic cardiomyopathy is a disorder of the heart muscle in people with diabetes. "Although it has been recently suggested that lncRNA, sST2 and galectin-3 may be promising biomarkers for diabetic cardiomyopathy detection as their plasma/serum levels correlate with the early stages of diabetic cardiomyopathy, further validation studies are necessary." (PMID 34441977, 2021).
encephalitis (7 papers, 2018 to 2026). An acute inflammatory process affecting the brain parenchyma. "In murine encephalitis models induced by Junín virus and by encephalomyocarditis virus, galectin-3 is upregulated in the activated microglia and serves as a diagnostic marker for neuronal degeneration." (PMID 36823664, 2023). "Interestingly, a few galectin-3 positive cells were detected in cerebellum microlesions during the immediate-early phase of encephalitis—as early as 48h –after EMCV inoculation." (PMID 30673749, 2019). "However, viral encephalitis induces CD4+ and CD8+ T cell infiltration and more Lgals3/MAC2-expressing macrophages surrounding dense-core Aβ plaques, which appear more compacted in JHMV-infected 5xFAD brains compared to uninfected 5xFAD controls." (PMID 42124663, 2026).
gastric tumor (7 papers, 2014 to 2024). "However, the tumors that were xenografted by overexpressed hTERT and depleted galectin-3 cells were significantly smaller than those prepared by overexpressed hTERT cells, suggesting that the hTERT-promoted gastric tumor growth was regulated by galectin-3." (PMID 27494887, 2016). "Therefore, we confirmed that TERT expression was also significantly regulated by galectin-3 in in vivo gastric tumors." (PMID 27494887, 2016). "Furthermore, analysis of 20 primary human gastric tumors revealed an overall positive correlation between increased active expression of galectin-3 and elevated neogenin-1 expression, except in 6 tissues." (PMID 24930499, 2014).
Hashimoto thyroiditis (7 papers, 2004 to 2023). An autoimmune disorder caused by the production of autoantibodies against thyroid tissue. "They found that galectin-3 expression is also present in Hashimoto thyroiditis and this reveals some limitations in nodule or multiple nodules of benign character." (PMID 23658855, 2010). "However, the expression of cytokeratin-19, galectin-3, HBME1, and loss of expression of CD56 are also detected in 20%, 20–40%, 20%, and 7–90% of patients with Hashimoto’s thyroiditis, respectively." (PMID 30428594, 2018). "However if the diagnosis of Hashimoto thyroiditis is excluded, then the usefulness of the galectin-3 in the diagnosis of malignancy still remain very high." (PMID 23658855, 2010). "Finally, none of the five unspecific chronic thyroiditis showed expression of galectin-3 (data not shown)." (PMID 15292926, 2004).
HIV-1 infection (7 papers, 2017 to 2024). The type species of lentivirus and the etiologic agent of acquired immunodeficiency syndrome (AIDS). "Exosomes derived from HIV-infected dendritic cells can transmit HIV-1 infection through fibronectin and galectin-3 and induce robust viral replication." (PMID 36823664, 2023). "Addition of anti-fibronectin antibody and β-lactose, a galectin-3 antagonist, significantly blocked DC exosome-mediated HIV-1 infection of T-cells." (PMID 29093555, 2017). "Moreover, in HIV-1 infection, galectin-3 interacts with Alix, which is known to coordinate with the endosomal sorting complex required for transport (ESCRT), through its NTD that stabilizes the Alix-Gag p6 complex and promotes HIV-1 budding." (PMID 36823664, 2023). "Based on our data, we proposed that in the early phase of HIV-1 infection, the Tat could bind to galectin-3 promoter and subsequently trigger cellular galectin-3 expression." (PMID 32326345, 2020).
hyperaldosteronism (7 papers, 2014 to 2025). Overproduction of aldosterone by the adrenal glands, which may lead to hypokalemia and/or hypernatremia. "In our study, plasma levels of galectin-3 were closely associated with hyperaldosteronism and vascular dysfunction and fibrosis." (PMID 28478264, 2017). "Besides, it has been shown that increased expression of galectin-3 in experimental hyperaldosteronism is related to cardiac fibrosis and dysfunction." (PMID 35208606, 2022). "In addition, this is the first study to provide human evidence of increased galectin-3 secretion in patients with hyperaldosteronism and the effect of adrenalectomy on galectin-3 level." (PMID 25180794, 2014).
Hypercholesterolemia (7 papers, 2016 to 2025). An increased concentration of cholesterol in the blood. "In response to d-flow under hypercholesterolemia, all MΦ clusters significantly accumulated, most notably MΦ3 and MΦ4 that highly expressed the markers of foam cells (Trem2, Lgals3, Gpnmb, Spp1, Lpl, and Fabp5)." (PMID 40092444, 2025). "Collectively, these findings show that in the setting of hypercholesterolemia, SMC-Abca1/Abcg1 deficiency induces bladder wall SMC lipid accumulation, bladder wall thinning, loss of SMC markers, and an increase in Lgals3+ SMCs, macrophage-like, and fibroblast-like cells." (PMID 39931819, 2025).
hypertrophic cardiomyopathy (7 papers, 2018 to 2025). A condition in which the myocardium is hypertrophied without an obvious cause. "In patients with hypertrophic cardiomyopathy, galectin-3 expression levels were proportionally elevated according to the degree of hypertrophy." (PMID 34722704, 2021).
lupus nephritis (7 papers, 2016 to 2023). Glomerulonephritis in the context of systemic lupus erythematosus. "Galectin-3 expression levels were determined in peripheral blood mononuclear cells (PBMCs) of SLE patients for the association with lupus nephritis (LN) or correlation of SLE disease activity index 2000 (SLEDAI-2K)." (PMID 37298447, 2023). "In an analysis of kidney tissue from patients with lupus nephritis, LGALS3—the interferon-regulated gene that encodes Gal3—was directly correlated with disease activity." (PMID 36909244, 2023). "Patients with SLE nephritis had higher serum galectin-3 levels and glomerular galectin-3 expression in renal tissue, which reflected disease activity." (PMID 27089335, 2016). "Glomerular galectin-3 expression was noted in 81.8% (72/88) of patients with SLE nephritis but not in the five controls." (PMID 27089335, 2016).
prostate tumor (7 papers, 2011 to 2023). "Compared to the normal tissue, the levels of CENPA, ADCK5, FOXM1, TFAP4, and MAPK were up-regulated in prostate tumor tissue, with a decrease in the expression of LGALS3 and BAG3." (PMID 36891298, 2023).
squamous cell carcinoma (7 papers, 2010 to 2024). A carcinoma arising from squamous epithelial cells. "Patients with squamous cell carcinoma had decreased galectin-3 levels compared to those with adenocarcinoma (p = 0.0019)." (PMID 38539500, 2024). "Galectin-3 level was elevated in patients with adenocarcinoma compared to squamous cell carcinoma patients and lower in patients exposed to chemotherapy." (PMID 38539500, 2024). "The results obtained from analysis of data from patients suffering from advanced squamous carcinoma of the larynx and oropharynx revealed that galectin-3 expression in tumor cells is positively and significantly related to prognosis." (PMID 23658855, 2010). "The differences in galectin-3 levels among patients with squamous cell carcinoma and adenocarcinoma may have future clinical treatment implications as galectin-3 inhibitors are currently in development." (PMID 38539500, 2024). "It is the first study to demonstrate that galectin-3 levels are elevated in adenocarcinoma patients compared to patients with squamous cell carcinoma, which may have future treatment implications with the development of galectin-3 inhibitors." (PMID 38539500, 2024). "Not only galectin-3 can be used as a marker in squamous cell carcinomas, expression of galectin-7 seems to be significantly reduced in malignant cells of squamous epithelia of both ectodermal and endodermal origin, thus allowing use of galectin-7 as differentiation marker of epithelial malignancies." (PMID 23658855, 2010). "Higher expression of galectin-3 in basal cell carcinoma (BCC) and squamous cell carcinoma (SCC) has been observed." (PMID 33150039, 2020). "This should be further examined in clinical trials and may influence future trial design for galectin-3 inhibitors, including their subgroup analysis, as squamous cell carcinoma and non-squamous cell carcinoma (including adenocarcinoma) are currently treated with different regimens." (PMID 38539500, 2024).
uveal melanoma (7 papers, 2022 to 2025). A melanoma derived from melanocytes of the uveal tract. "Supporting this mechanism, data from uveal melanoma cell lines demonstrated colocalization of galectin-3 with MCAM on the cell surface, as well as a dose-dependent increase in AKT phosphorylation following exposure to exogenous galectin-3." (PMID 41388158, 2025). "This study showed that galectin-3 is naturally associated with MCAM on the surface of both skin and uveal melanoma cells." (PMID 36291660, 2022). "Furthermore, this study found a high representation of lymphocyte activation gene-3 (LAG-3) and Galectin-3 in uveal melanoma." (PMID 37237550, 2023). "Our exploratory survival analysis further indicated that elevated LGALS3 expression correlates with poorer overall survival in PDAC and several other tumor types, including low-grade glioma (LGG), uveal melanoma (UVM), and kidney renal papillary cell carcinoma (KIRP)." (PMID 41153387, 2025).
Abdominal obesity (6 papers, 2021 to 2025). Excessive fat around the stomach and abdomen. "High Gal3BP was defined as ≥3.3 μg/ml, high sCD163 as ≥0.6 μg/ml, high galectin-3 as ≥2.6 ng/ml, impaired glycemic control as HbA1c >70 mmol/mol (>8.6%) and abdominal obesity as waist circumference ≥ 1.02 m for men and ≥ 0.88 m for women." (PMID 34045984, 2021).
acute respiratory distress syndrome (6 papers, 2022 to 2024). Progressive and life-threatening pulmonary distress in the absence of an underlying pulmonary condition, usually following major trauma or surgery. "Elevated galectin-3 levels were associated with increased risks of mortality, need for intensive care, and severe acute respiratory distress syndrome." (PMID 39465409, 2024). "Increased levels of galectin-3 in serum have been reported to be associated with worse outcomes and lower survival in patients with acute respiratory distress syndrome (ARDS)." (PMID 38674175, 2024). "The authors also reported that higher levels of galectin-3 were associated with admission to the ICU and a higher risk of acute respiratory distress syndrome (ARDS)." (PMID 35326373, 2022).
Allergy (6 papers, 2009 to 2020). An allergy is an immune response or reaction to substances that are usually not harmful. "Galectin-3, formerly identified as IgE-binding protein, is also suspected to play a role in allergy pathways." (PMID 24859692, 2014).
anemia (6 papers, 2015 to 2026). A reduction in the number of red blood cells, the amount of hemoglobin, and/or the volume of packed red blood cells. "During infection, the TRM2 cluster strongly expresses the M1-associated Macrophage migration Inhibitory Factor gene Mif, and Galectin-3 gene Lgals3, that are actively involved in trypanosomosis associated anemia." (PMID 36420267, 2022). "Hereby, T. brucei infected galectin-3 deficient mice exhibit greatly reduced anemia levels coinciding with a restored iron homeostasis and an increased IL-10 level that in turn leads to reduced liver destruction." (PMID 26090446, 2015). "Galectin-3 (Gal-3), a lectin contributing to the onset and persistence of type-1 inflammatory responses and phagocytosis, was shown to be involved in trypanosomosis-associated anemia development." (PMID 26090446, 2015). "Collectively, these results suggest that the M1-type MYPS cell associated molecules galectin-3 and MIF both promote the most prominent pathological features of experimental trypanosome infections (anemia and liver injury)." (PMID 26090446, 2015). "A comparative gene expression analysis between M1 and M2 cells identified galectin-3 (Gal-3) and macrophage migration inhibitory factor (MIF) as novel M1-promoting factors, possibly acting synergistically and in concert with TNF-α during anemia development." (PMID 29497418, 2018). "Finally, a comprehensive laboratory evaluation iswarranted to rule out concomitant conditions such as hypothyroidism, renalfailure, and anemia; and to assess for cardiomyopathic changes (hs-Troponin,brain natriuretic peptide, ST2, galectin-3)." (PMID 39076279, 2023).
astrocytoma (6 papers, 2021 to 2025). "LGALS3 mRNA, which encodes galectin-3 (Gal-3), was increased 28-fold in high-grade astrocytoma compared to normal brain (*P < .05)." (PMID 34131649, 2021). "In line with our observations, in astrocytoma or nasopharyngeal carcinoma cells, the knockdown of galectin-3 by si- or sh-RNA led to a reduced viability and migration." (PMID 40806748, 2025). "Immunohistochemistry staining was performed to detect galectin-3/GSK3B protein expression in patients with astrocytoma." (PMID 37185758, 2023). "In our study, galectin-3 protein expression was significantly positively correlated with the World Health Organization (WHO) astrocytoma grade and overall survival time." (PMID 37185758, 2023). "Although several studies have examined the role of galectin-3 in cancer, there are very few reports on this protein in the context of astrocytoma." (PMID 37185758, 2023). "This study aims to validate the correlation between the clinical outcomes and protein expression of galectin-3/GSK3B in astrocytoma." (PMID 37185758, 2023). "Multivariate analysis revealed that galectin-3 expression was an independent prognostic factor for astrocytoma." (PMID 37185758, 2023). "In conclusion, our results propose that GSK3B and galectin-3 are involved in important molecular changes that are significantly related to the WHO astrocytoma grade and are independent biomarkers for astrocytoma prognosis." (PMID 37185758, 2023). "However, knockdown of GSK3B/galectin-3 inhibited cell proliferation, invasion, and migration of astrocytoma cells and galectin-3 mediated tumor progression by upregulating GSK3B protein expression." (PMID 37185758, 2023). "Therefore, GSK3B is upregulated by galectin-3 in astrocytoma." (PMID 37185758, 2023). "However, the clinicopathological role of GSK3B and galectin-3 in astrocytoma remains unelucidated." (PMID 37185758, 2023). "Galectin-3 and GSK3B protein expression were significantly positively correlated with the World Health Organization (WHO) astrocytoma grade and overall survival time." (PMID 37185758, 2023). "Immunohistochemical staining of galectin-3 and GSK3B was analyzed to determine the relationship between protein expression and the clinical parameters of patients with astrocytoma." (PMID 37185758, 2023). "In our study, we discovered that knockdown of galectin-3 attenuated cell proliferation, migration, and invasion and inhibited the Ki-67, VEGF, and cyclin D1 protein expression in astrocytoma cells." (PMID 37185758, 2023). "Multivariate analysis revealed that WHO grade, galectin-3 expression, and GSK3B expression were independent prognostic factors for astrocytoma." (PMID 37185758, 2023). "Therefore, our study aims to validate not only the relationship between the clinical outcomes but also the protein expression of galectin-3 and GSK3B and the correlation between galectin-3 and GSK3B in astrocytoma." (PMID 37185758, 2023). "Therefore, galectin-3 and GSK3B were independent prognostic biomarkers in the astrocytoma cases that were studied." (PMID 37185758, 2023). "Both galectin-3 and GSK3B are potential prognostic markers and may be considered as anticancer target genes for astrocytoma therapy." (PMID 37185758, 2023). "Therefore, galectin-3 and GSK3B are potential prognostic markers, and their genes may be considered to be anticancer targets for astrocytoma therapy." (PMID 37185758, 2023). "However, the correlation between the protein expression of galectin-3/GSK3B and the clinical parameters of astrocytoma has not been reported." (PMID 37185758, 2023).